IL5 (interleukin 5)
Diseases named in the same sentence as IL5 in open-access papers (continued):
Sharing a sentence is not in itself a finding about the gene and the disease.
asthma (continued). "With regard to asthma, a blockade of TL1A with neutralizing antibodies suppressed airway inflammation and levels of IL-4, IL-5, and IL-13 in a murine model of asthma." (PMID 38540714, 2024). "In a case where asthma developed following pembrolizumab administration, increased levels of IL-5 cytokine in the blood were observed, suggesting a possible link between PD-1 inhibitor administration and the onset of asthma through IL-5 cytokine production." (PMID 39200350, 2024). "BAs such as anti-IgE, anti-IL5, and anti-IL-4/IL-13 monoclonal antibodies (mAb) were found to be effective in the CRSwNP treatment of patients with severe asthma, with the most significant reduction being observed in the anti-IL-4R-mAb-receiving group." (PMID 38541174, 2024). "The pathophysiology of asthma was strongly influenced by Th2 cytokines such as IL-4, IL-5, and IL-13." (PMID 37750936, 2024). "Benralizumab, dupilumab, and reslizumab are mAbs to IL-5R, IL-4R, and IL-5, respectively, the biologics currently approved worldwide for allergic diseases such as asthma and atopic dermatitis." (PMID 38419685, 2024). "Mepolizumab and reslizumab are anti-IL-5 monoclonal antibodies that have been shown to reduce asthma exacerbation rates by ~50% relative to placebo when used as add-on therapy in patients with exacerbation-prone severe eosinophilic asthma." (PMID 39194521, 2024). "Monoclonal antibodies (mAbs) targeting specific cytokines, such as IL-5, IL-4/IL-13, and IgE, have provided significant benefits for patients with specific asthma phenotypes." (PMID 39902079, 2024). "In contrast, asthma can increase levels of IL-5 [odds ratio (OR) = 1.112, 95% confidence interval (CI): 1.009–1.224, P = 0.032] and IL-9 (OR = 1.111, 95% CI: 1.013–1.219, P = 0.025)." (PMID 39175819, 2024). "It is well known that Th1/Th2 immune dysregulation is a common feature of asthmatic airway inflammation and that cytokines IL-4, IL-5, IL-6 and IL-13 produced by Th2 cells play an important role in asthma pathogenesis." (PMID 38579176, 2024). "IL-5 has significant effects on allergy and asthma due to its role in eosinophile proliferation and differentiation, which have been well documented." (PMID 39062104, 2024). "T2-high asthma, also known as allergic asthma, is featured by hypersecretion of interleukin (IL)-4, IL-5, and IL-13, elevated eosinophil counts, and total IgE and mucus overproduction." (PMID 38168709, 2024). "The discovery of the molecular mechanisms involved in the pathogenesis of asthma has enabled the development of anti-eosinophilic biologic therapies targeting IL-5 (mepolizumab and reslizumab) or its receptor (benralizumab)." (PMID 39064286, 2024). "Anti-IL-5/anti-IL-5R has proven to be a very effective added therapeutic option for asthma patients to reach these goals." (PMID 39726457, 2024). "In contrast, a study with patients with severe asthma showed that the treatment with anti-IL-5 promoted the downregulation of miR-27b-3p, improved lung function, and decreased peripheral eosinophil counts." (PMID 38337625, 2024). "Three therapeutic antibodies have been approved for the treatment of severe asthma with eosinophilic inflammation: mepolizumab and reslizumab (anti-IL-5 antibodies) as well as benralizumab (antibody against the α-chain of the human IL-5 receptor (IL-5Rα))." (PMID 39600395, 2024). "The treatments of the glucocorticoid as well as Ro5-4864 and PK 11,195 were found to make a decrease in the concentration of IL-5, indicating an inhibitory effect on the type 2 inflammation in glucocorticoid-sensitive asthma." (PMID 38641850, 2024). "ILC2s reside on mucosal surfaces, including the lungs, and are capable of producing type 2 cytokines such as interleukin-5 (IL-5) and interleukin-13 (IL-13), which are pivotal in the pathogenesis of allergic disorders and asthma." (PMID 39346946, 2024). "Compared to controls, bronchial biopsy results in both early and advanced asthma patients showed increased IL-5 mRNA expression." (PMID 39175819, 2024).
asthma (continued). "According to the molecular pathways, not only in asthma pathogenesis but also in IgE-dependent AD, the biomolecular mechanisms of IL-5 action are indispensable for eosinophil growth, differentiation, and migration." (PMID 39062104, 2024). "For example, the ILC2s from patients with asthma secreted more IL-5 and IL-13 compared to the ILC2s derived from healthy controls." (PMID 38254421, 2024). "Severe eosinophilic asthmatics on anti-IL-5 biologic therapy have shown an improvement in asthma symptoms, with a reduction in the number of exacerbations." (PMID 38495619, 2024). "The children with asthma had an inflammatory profile that was characterized by increased levels of several pro-inflammatory cytokines, including IL-2, IL-5, IL-13, IL-17A, IL-22, IL-33, TNF-α, and reduced level of anti-inflammatory cytokine, IL-10." (PMID 39902293, 2024). "While most biologics targeting eosinophils have proven effective in asthma, it is now known that only antibodies against IL-5, such as mepolizumab, also have a significant impact on CRSwNP." (PMID 39726672, 2024). "Oppositely, ACT scores and lung function rose after the start of biologic treatment, confirming the improvement granted by anti-IL5/IL5r on severe asthma symptoms." (PMID 38327518, 2024). "After 3‐h treatment with IL‐5 or IL‐17, the levels of mRNA expression in eosinophils derived from patients with asthma started exhibiting a declining trend." (PMID 39575691, 2024). "Given that Th2 cells secrete IL-5 and IL-13 during asthma exacerbation, we further examined the effect of CBD-X extract on the secretion of these cytokines." (PMID 39459021, 2024). "Chi3l1 siRNA also decreases the expression of eosinophilic airway inflammation-related factors, including IL-5, eotaxin, and GM-CSF, at the mRNA and protein levels in an epithelial cell model of asthma, thus reducing airway inflammation." (PMID 39769202, 2024). "The pathogenesis of T2-high asthma is chiefly orchestrated by interleukins (IL)-4, IL-5, and IL-13 and is usually accompanied by eosinophil infiltration." (PMID 39685611, 2024). "Studies have shown that simvastatin can decrease the levels of IL-4 and IL-5 in bronchoalveolar lavage fluid.Simvastatin prevented airway remodeling in asthma at an early stage." (PMID 38961500, 2024). "HRV infection can cause the release of pro-inflammatory factor IL-25 from respiratory epithelial cells, further promoting pulmonary production of type 2 immune/inflammation effectors IL-4, IL-5, IL-13, and IgE, to exacerbate asthma allergic responses." (PMID 38780281, 2024). "These biologic agents, mainly monoclonal antibodies, are aimed at crucial molecular pathways involved in asthma’s pathogenesis, such as interleukin-5 (IL-5), interleukin-4 (IL-4), interleukin-13 (IL-13), and immunoglobulin E (IgE)." (PMID 38525773, 2024). "These factors can explain the paradox of high IL-5 levels despite lower eosinophil count in the overweight/obese and asthma group as compared to normal-weight and asthma group." (PMID 39902293, 2024). "Together, despite differences across models, mouse models supported a focus on therapeutic targeting of the IL-4/IL-4Rα/IL-5/IL-13 pathways for asthma treatment." (PMID 40047886, 2024). "For example, αMβ2 (CD11b/CD18) is upregulated by IL-5 and other mediators, while intermediate and high-activity states of β1 and β2 integrins correlate with asthma severity and eosinophil activation." (PMID 39518415, 2024). "Many studies on both animal and human models of asthma have shown that there is a close correlation between IL-5 and eosinophilic inflammation." (PMID 39062104, 2024). "Particular emphasis is placed on describing the phenotypic and functional roles of these eosinophil subtypes in asthma, as well as the phenotypic changes induced by clinical therapy with the anti-IL-5 biologic agent, mepolizumab." (PMID 39335525, 2024).
asthma (continued). "Interleukin-5 (IL-5) is a cytokine essential to the survival and activation of eosinophils, which are key players in the inflammatory process of asthma." (PMID 39518722, 2024). "Genetically predicted asthma was positively associated with elevated levels of IL-5 and IL-9, indicating the downstream effects of IL-5 and IL-9 on asthma." (PMID 39175819, 2024). "Elevated levels of T helper 2 cell (Th2)-related cytokines such as IL-4, IL-5, IL-13 along with immunoglobulin E (IgE) characterize T2 asthma." (PMID 39064286, 2024). "In patients with severe asthma and an increased eosinophil count in the sputum or blood with frequent exacerbations, an anti-IL-5 Ab or an anti-IL-5R Ab reduces the blood eosinophil count and asthma exacerbation frequency." (PMID 38785953, 2024). "Biologics targeting the IL-4, IL-5, and IL-13 pathways are generally effective in reducing asthma exacerbations and improving lung function." (PMID 39275297, 2024). "The interaction analysis showed that combination of both asthma and obesity had significant effects on IL-5, IL-10, IL-17A, IL-33, TNF-α, and leptin, but the effects were not synergistic or additive." (PMID 39902293, 2024). "Tozorakimab reduced biomarkers of inflammation, including serum IL-5, IL-13 and blood eosinophils, in a phase 1 study and is being evaluated in a phase 2 study in patients with asthma (ClinicalTrials.gov: NCT04570657)." (PMID 38609094, 2024). "The immune signature of asthma involves eosinophilia, IgE induction of airway smooth muscle, and increased levels of IL-4, IL-5, and IL-13." (PMID 39481080, 2024). "Th2-related inflammatory cytokines, such as IL4 and IL5, are increased in asthma patients with RSV infection." (PMID 39632661, 2024). "Utilized in the management of asthma, Mepolizumab and Benralizumab, are monoclonal antibodies that target IL-5 and IL-5Rα, respectively." (PMID 38541674, 2024). "The arsenal of biologics available for asthma patients is extensive, with anti-IgE, anti-IL-5, anti-IL-4/IL-13 and anti-TSLP currently in use." (PMID 39726672, 2024). "The most common inflammatory endotype is type 2 (T2)-high asthma, characterised by high levels of T2 inflammatory biomarkers including eosinophils, exhaled nitric oxide, IgE, interleukin (IL)-5 and IL-13." (PMID 38609094, 2024). "Mucous metaplasia can be triggered by inflammatory mechanisms and has been extensively studied in the context of Th2-dependent cytokines IL-4, IL-5, and IL-13, which play an important role within asthma." (PMID 39239645, 2024). "During this era, the roles of primary effector cells (such as mast cells and basophils) and type-2 (T2) cytokines (such as interleukin (IL)-4, IL-5 and IL-13) in asthma were identified." (PMID 39694589, 2024). "In clinical studies, anti-TSLP Ab treatment was shown to suppress asthma exacerbation in patients with severe asthma, inhibit eosinophilic inflammation in the airway, and to decrease the concentrations of IL-5 and IL-13 in serum." (PMID 39624446, 2024). "Elevated levels of IL-5 can be found in induced sputum from patients with allergic asthma and patients experiencing acute asthma exacerbations, as well as in their serum." (PMID 39062104, 2024). "Upon activation, ILC2s produce abundant amounts of IL-5 and are involved in the development of persistent airway eosinophilia in asthma despite treatment with systemic steroids." (PMID 39452061, 2024). "We found that the administration of probiotics significantly reduced the asthma severity of the mice, as well as serum IgE and IL-5." (PMID 38674852, 2024). "Asthma, aspirin intolerance, peripheral eosinophilia, interleukin-5 (IL-5) expression, T2 profile, and intense sinus opacification have been noted to be independent predictors of the condition in different studies." (PMID 39328679, 2024). "The ability of CBD-X to reduce key inflammatory markers of asthma—such as IgE, IL-4, IL-5, and IL-13—in a murine asthma model further supports its anti-inflammatory effects." (PMID 39459021, 2024).
asthma (continued). "Th2 cells are crucial in the pathogenesis of asthma due to their secretion of IL-5 and IL-13, which promote eosinophilic inflammation and BHR." (PMID 39459021, 2024). "There are currently several classes of biologics approved for severe asthma including anti-immunoglobulin E, anti-interleukin-5/interleukin 5R, anti-interleukin 4/interleukin 13R, and anti-thymic stromal lymphopoietin." (PMID 38291489, 2024). "Asthma induces bronchial inflammation, triggering the accumulation of inflammatory cytokines (such as IL-4, IL-5, and IL-13) and free radicals." (PMID 38931275, 2024). "Antibodies targeting IL5 (Mepolizumab) or IL5 receptor α-chain (Benralizumab) reduce the asthma exacerbation rate and the daily dose of oral corticosteroids." (PMID 38711519, 2024). "More recently a subset of NK cells producing IL-4 and IL-5 have been described in atopic dermatitis and asthma." (PMID 39034635, 2024). "Several observational studies have also demonstrated changes in IL-5 levels during the onset of asthma." (PMID 39175819, 2024). "There is also evidence showing that tiotropium minimised the excessive release of IL-5 and IL-13 in human peripheral blood mononuclear cells derived from asthma patients." (PMID 38419021, 2024). "For example, PLA2 contributes to anti-helminth defense by hydrolyzing membrane phospholipids (Th2-defence, production of IL4 and IL5 cytokines, allergy/asthma)." (PMID 38674024, 2024). "Schistosoma mansoni recombinant proteins (Sm22.6 and Sm29) or antigens derived from schistosoma tegument regulate IL‐5 and IL‐13 production and enhance eosinophil production in asthma models." (PMID 38888451, 2024). "Interleukin-5 mRNA is found in eosinophils from patients with asthma, celiac disease, and eosinophilic heart disease, and IL-5 expression by eosinophils has been confirmed in atopic dermatitis." (PMID 38672221, 2024). "PCSK9 inhibitors (evolocumab, alirocumab) for hypercholesterolemia, neprilysin inhibitors for heart failure, IL-5 inhibitors for asthma." (PMID 39539858, 2024). "IL-5 is of notable importance in the development of asthma, especially in cases of allergic asthma marked by eosinophilic inflammation." (PMID 39407835, 2024). "IL-5 is thus fundamental to severe asthma, and this understanding is recognized in the guideline recommendations for biologic therapies that target IL-5 in the management of this disease." (PMID 39465531, 2024). "Numerous drugs are available to treat asthma presently, including β2-adrenoceptor agonists, corticosteroids, and monoclonal antibodies targeting key cytokines (i.e., IL-5, IL-13, and IL-4)." (PMID 38340268, 2024). "Th2 cells play a key role in asthma pathogenesis by secreting cytokines such as IL-4, IL-5, and IL-13, crucial for promoting allergic inflammation." (PMID 39518415, 2024). "Mepolizumab is an IL-5 antagonist monoclonal antibody that was approved first for severe asthma with eosinophilic inflammation." (PMID 38690264, 2024). "The OVA-induced IL-5 cytokine sensitization was suppressed by high doses of probiotics relieving the inflammatory cell infiltration in the lungs; thus, the asthma allergic reaction was suppressed." (PMID 38674852, 2024). "There are several biological drugs currently available to treat severe asthma: anti-IL-5 (mepolizumab, reslizumab, benralizumab), anti-IgE (omalizumab), anti-IL-4/IL-13 (dupilumab), and anti-TSLP (tezepelumab) agents." (PMID 39685611, 2024). "The study found that this combination significantly reduced the presence of Th2/Th17-derived cytokines (IL-4, IL-5, IL-13, IL-17A), immunoglobulin E, and leukotriene C4 in bronchoalveolar lavage fluid and serum, key contributors to allergies and asthma." (PMID 39857357, 2024). "Many patients with severe asthma are treated with monoclonal antibodies which target the asthma inflammatory pathways, such as those targeting IgE, Interleukin (IL)-5 and its receptor, and the IL-4 receptor α subunit." (PMID 38713421, 2024).
asthma (continued). "Th2 immune response, which induces the secretion of IL‐4, IL‐5, and IL‐13 by both innate and adaptive immune cells, is the main pathway of most parasitic immunity and immunopathological processes in asthma." (PMID 38888451, 2024). "On the contrary, the clinical analysis indicated that asthma development, including its exacerbation, was less likely in the anti-IL-5 treatment group compared to the placebo group." (PMID 38308249, 2024). "Mouse models of OVA-induced allergic airway inflammation show several characteristics of human asthma, including increased serum IgE concentrations, eosinophil infiltration, and increased levels of Th2 cytokines (IL-4, IL-5, and IL-13)." (PMID 39594470, 2024). "Nasopharyngitis, asthma worsening, headache, upper respiratory tract infection, and bronchitis were the 5 most common AEs reported in the anti-IL-5 treatment group (noted in all sub-treatment cohorts)." (PMID 38308249, 2024). "The number of IL-5-, IL-10-, and IL-13-producing peripheral blood mononuclear cells (PBMCs) derived from all children at the asthma camp significantly (p < 0.05) decreased in the water aerosol group." (PMID 38398384, 2024). "In BALF, compared with OVA-induced asthma mice, Sophoraflavanone G significantly reduced the levels of IL-4, IL-5, IL-13, TNF-α, IL-6, CCL11, and CCL24." (PMID 39759448, 2024). "Anti-IL-5 therapies have shown promise by reducing eosinophil levels and decreasing the frequency of asthma exacerbations in patients with severe eosinophilic asthma." (PMID 39518415, 2024). "The outcomes of a recent study revealed a connection between CRSwNP with eosinophilic inflammation and an increase in both the quantities of ILC2s and the production of IL-5 by ILC2s, particularly in individuals concurrently diagnosed with asthma." (PMID 38680486, 2024). "A number of monoclonal antibody therapies targeting IgE (such as omalizumab) or eosinophilic inflammation (such as mepolizumab, an anti‐IL5 monoclonal antibody) have been developed for severe asthma but have utility in ABPA." (PMID 36403106, 2023). "This suggests that activated IL-5 and IL-4/IL-13 pathways can simultaneously contribute to airway inflammation in some cases of severe asthma." (PMID 37298514, 2023). "Following upper respiratory viral infections, the levels of induced sputum IFN-γ in asthma patients were increased prior to Th2 cytokines IL-4 and IL-5." (PMID 37865742, 2023). "The immunomodulatory properties of macrolides are well-recognized; for example, asthma patients receiving azithromycin exhibit lower IL-5 expression in CD4+ cells isolated from peripheral blood mononuclear cells." (PMID 37347185, 2023). "Molecular pathophysiology of T2 asthma is fuelled by activated GATA-3+ CRTH2+ ILC2s as well as Th2 cells that produce substantial amounts of the hallmark type 2 cytokines: IL-4, IL-5, and IL-13." (PMID 37199256, 2023). "Unlike corticosteroids which target an unspecified range of cells, biological therapies specifically target inflammatory cytokines (IL-4, IL-5, and IL-13), of T2-high asthma." (PMID 38259298, 2023). "Sputum eosinophil count can be used to guide therapy in patients with asthma, and serum eosinophil count can be used to monitor biochemical responses in patients treated with anti-IL-5." (PMID 38203353, 2023). "Patients with severe asthma have abnormal production of type 2 cytokines, whereas IL-5 is the main mediator of eosinophilic inflammation." (PMID 36979655, 2023). "Mepolizumab is a monoclonal antibody targeting IL-5, which has effectively decreased asthma exacerbation rates in severe eosinophil-driven asthma." (PMID 37189529, 2023). "A total of 142 patients (57 males, 85 females and mean age 58.2 years old) were being treated with anti-IL-5 biologics under the LTHT’s severe asthma clinic, with a mean duration of 3.5 years on therapy." (PMID 38114196, 2023).